NLRP3 (NLR family pyrin domain containing 3)
Diseases named in the same sentence as NLRP3 in open-access papers (continued):
Sharing a sentence is not in itself a finding about the gene and the disease.
neurodegenerative disease (continued). "The NLRP3 inflammasome has attracted attention from researchers and the pharmaceutical industry, as it participates in many inflammatory and neurodegenerative diseases." (PMID 35669789, 2022). "NLRP3 inflammasome activation is known to be an indicator of the development of neurodegenerative diseases and is also a pre-requisite for neuroinflammation initiation." (PMID 36139756, 2022). "More and more experimental evidence show that the activation of NLRP3 inflammasome is closely related to neurodegenerative diseases." (PMID 35250595, 2022). "NLRP3 inflammasome major role is to detect inflammation and immune system-related disorders, and also in the pathogenesis of several neurodegenerative diseases." (PMID 36660080, 2022). "Many recent studies found that key factors that cause neurodegenerative diseases, such as 1-methyl-4-phenyl-1,2,3,6-tetrahydropyridine (MPTP), amyloid-β (Aβ), and Tau, are also activation signals for the NLRP3 inflammasome." (PMID 35219323, 2022). "Although other air pollutants have been shown to activate NLRP3 inflammasome and mediate pulmonary, cardiovascular, and neurodegenerative diseases, the effect of CS on the activation/inhibition of NLRP3 is still controversial and under debate." (PMID 35428946, 2022). "More and more experimental evidence showed that the activation of NLRP3 inflammasome is closely related to neurodegenerative diseases." (PMID 35993019, 2022). "Emerging evidence indicates that the NLRP3 inflammasome is involved in the innate immune response in neurodegenerative diseases." (PMID 35918778, 2022). "Combining the use of the specific inhibitors of the NLRP3 inflammasome with autophagy inducers is more effective than one single treatment in cellular or animal models of neurodegenerative diseases." (PMID 36704504, 2022). "NLRP3 inflammasome activity has been shown to be directly attributable to the pathogenesis of some of the misfolded protein aggregates in neurodegenerative diseases." (PMID 35185469, 2022). "Microglial hyperactivation of the NLRP3 inflammasome has been well-documented in various neurodegenerative diseases, including PD." (PMID 36704504, 2022). "Strengthening autophagy can regulate the expression of NLRP3 inflammasome to reduce neuroinflammation in neurodegenerative disease and protect neurons." (PMID 36262883, 2022). "Recent studies have implicated an important role for the NLRP3 inflammasome and the ASC speck in the propagation and spreading of neuroinflammation and misfolded protein aggregation in neurodegenerative diseases and are reviewed here." (PMID 35185469, 2022). "This review aims to summarise current literature on the role of the NLRP3 inflammasome in the pathogenesis of neurodegenerative diseases, and recent work investigating NLRP3 inflammasome inhibition as a potential future therapy." (PMID 33776778, 2021). "Previous studies have mainly focused on the role of NLRP3 inflammasome in microglia as well as its effects on neurodegenerative diseases in APP/PS1 mice and in humans." (PMID 34924922, 2021). "Activated NLRP3 inflammasome aggravates the pathology and accelerates the progression of neurodegenerative diseases." (PMID 34691027, 2021). "Data indisputably indicate that mitochondrial dysfunction in conjunction with NLRP3 activation contributes to the pathogenesis of neurodegenerative diseases, such as AD and PD." (PMID 34959622, 2021). "It is well documented that reactive astrocytes and activated microglia in the CNS contribute to neuroinflammation with their inflammatory responses, in which NLRP3 modulation has been reported to play a key role in neurodegenerative diseases." (PMID 34827148, 2021). "It has been documented that microbiota interact with NLRP3 inflammasome in the gut, and the NLRP3 inflammasome has been shown to be activated in several neurodegenerative diseases." (PMID 33916001, 2021).
neurodegenerative disease (continued). "Among inflammasomes, NLRP3 is the most studied and characterized, and its activation in neurodegenerative diseases mainly focuses on astrocytes and microglia." (PMID 34209586, 2021). "In this review, we discuss the role of mitochondrial dysfunction in the pathogenesis of selected neurodegenerative diseases, AD and PD, in the light of over-activated NLRP3." (PMID 34959622, 2021). "The nucleotide-binding oligomerization domain leucine-rich repeat and pyrin domain-containing protein 3 (NLRP3) inflammasome, one of the most intensively investigated inflammasomes, has been reported to play a key role in neurodegenerative diseases." (PMID 33670164, 2021). "Due to this convincing evidence connecting the NLRP3 inflammasome to muscle wasting, investigators have spent considerable efforts on determining whether NLRP3 inflammasome signaling is also involved in neuromuscular and neurodegenerative diseases associated with muscular dysfunction." (PMID 34199845, 2021). "Recently, more and more studies have indicated that inflammasomes are closely related to neurodegenerative diseases: activated NLRP3 was observed in AD." (PMID 34188608, 2021). "The present review includes a broadened approach to the role of mitochondrial dysfunction resulting in abnormal NLRP3 activation in selected neurodegenerative diseases." (PMID 34959622, 2021). "Given the role of the NLRP3 inflammasome in neuroinflammation, a number of studies has been conducted in the exploration of possible therapeutic pathways for neurodegenerative diseases through the inhibition of the NLRP3 inflammasome." (PMID 33670164, 2021). "Accordingly, targeting the NLRP3 inflammasome pathway is considered a therapeutic strategy for neurodegenerative diseases." (PMID 32751738, 2020). "Strong evidence suggested that the activation of NLRP3 inflammasome is a key factor to regulate microglial activation in neurodegenerative diseases." (PMID 32375810, 2020). "Activation of the NLRP3 inflammasome and pyroptosis has been reported in various disorders, including inflammatory and neurodegenerative diseases." (PMID 32903868, 2020). "The NLRP3 inflammasome is a core component of innate immunity, and dysregulation of NLRP3 inflammasome involves developing autoimmune, metabolic, and neurodegenerative diseases." (PMID 33424864, 2020). "The NLRP3 inflammasome can be activated by the abnormal protein aggregation that occurs in neurodegenerative diseases." (PMID 32792920, 2020). "Another important point to understand the role played by IL-1β liberated through NLRP3 activation in neurodegenerative diseases, is to characterize in detail the inflammasome expression and activation in CNS inflammatory cells." (PMID 33353046, 2020). "The nucleotide-binding oligomerization domain leucine-rich repeat and pyrin domain-containing protein 3 (NLRP3) inflammasome, which is one of the most intensively investigated inflammasomes, has been reported to play a key role in neurodegenerative diseases." (PMID 32792920, 2020). "The dysregulation of NLRP3 inflammasome activation has been demonstrated to participate in the pathogenesis of metabolic disorders and neurodegenerative diseases." (PMID 32582195, 2020). "NLRP3 inflammasome is a component of the innate immune response and different diseases, such as neurodegenerative diseases, are characterized by NLRP3 activation." (PMID 32867310, 2020). "Previous studies indicated that the activation of nod-like receptor family pyrin domain-containing 3 (NLRP3) inflammasome is a key factor to regulate microglial activation in neurodegenerative diseases." (PMID 32375810, 2020). "Knockdown of NOX4 by RNAi reduced NLRP3 activation, suggesting a potential target to reduce NLRP3-stimulated pathology in neurodegenerative disease." (PMID 32823544, 2020).
neurodegenerative disease (continued). "The identification of the calcium signaling pathway regulating mitochondrial fission and the NLRP3 inflammasome activation will be useful in the development of therapeutic strategies for the treatment of ethanol-related neurodegenerative diseases." (PMID 32787872, 2020). "The nucleotide-binding-domain (NBD)–and leucine-rich repeat (LRR)–containing (NLR) family, pyrin-domain–containing 3 (NLRP3) inflammasome drives pathological inflammation in a suite of autoimmune, metabolic, malignant, and neurodegenerative diseases." (PMID 31525186, 2019). "A typical example is NLRP3 which plays a key role in the pathogenesis of multiple neurodegenerative diseases such as PD and AD." (PMID 31496930, 2019). "Activation of NLRP3 inflammasome has been demonstrated a significant contribution to the progression of neurodegenerative diseases." (PMID 31118933, 2019). "The NLRP3 inflammasome plays important roles in the pathogenesis of metabolic diseases, neurodegenerative diseases and infectious diseases." (PMID 30944389, 2019). "The activation of NLRP3 inflammasome had been reported to be involved in neurodegenerative diseases, including postoperative cognitive change, and is closely related to mitochondrial ROS and mitophagy." (PMID 30918581, 2019). "In the last few years, numerous studies have been conducted in the exploration of therapeutic pathways against neurodegenerative diseases through the inhibition of the NLRP3 inflammasome." (PMID 30233319, 2018). "NLRP3 inflammasome is the main regulator to produce IL-1β and is considered to regulate the progression of several neurodegenerative diseases." (PMID 30107806, 2018). "The cleavage and maturation of IL-1β are activated by NLRP3 inflammasome, and the activation of NLRP3 inflammasome can contribute to pathophysiological processes involved in diabetic complications and neurodegenerative diseases." (PMID 29507694, 2018). "Our group has recently presented data in acute and chronic neurodegenerative disease models that different components of the NLRP3-inflammasome are allocated to astrocytes." (PMID 30261895, 2018). "Most of the inflammasomes contribute to the development of neuroimmune and neurodegenerative diseases such as the NLRP3 inflammasome, while some have anti-inflammatory properties such as NLRX1 inflammasome and NLRP12 inflammasome." (PMID 29849483, 2018). "On the other hand, the nucleotide-binding oligomerization domain-like receptor containing pyrin domain 3 (NLRP3) inflammasome is an essential regulator to produce IL-1β and is considered to regulate the progression of several neurodegenerative diseases." (PMID 30107806, 2018). "What’s more, amyloid-β can induce the activation of NLRP3 inflammasome in Alzheimer’s patients, which makes NLRP3 inflammasome a hot research target in neurodegenerative diseases." (PMID 28360909, 2017). "Among NLRs, NLRP3 inflammasome were found to be activated or highly expressed in glial cells following brain injury or in several neurodegenerative diseases." (PMID 28486969, 2017). "Neuroinflammatory cascades rely on the activation of NLRP3 inflammasome, which has been proved crucial in neurodegenerative diseases." (PMID 27652274, 2016). "We were interested in the potential implication of the NLRP3 inflammasome in neurodegenerative diseases and focused on in vitro activation of microglia and astrocytes by peptide aggregates related to these conditions." (PMID 26091541, 2015). "NLRP3 inflammasome is the major inflammasome pathway in neurons and microglia and its activation has implications in various neurodegenerative diseases, including AD, PD, HD, and MS, prion disease and other neuroinflammation-related disorders like brain stroke and injury." (PMID 41280719, 2025).
neurodegenerative disease (continued). "Overall, these results highlight the potential of certain Ramalin derivatives in modulating neuroinflammatory responses through NLRP3 inhibition, which could be advantageous for developing therapeutics targeting neurodegenerative diseases like AD." (PMID 40363835, 2025). "The NLRP3 inflammasome is also involved in other neurodegenerative diseases." (PMID 40854880, 2025). "Microglial pyroptosis, through the activation of the NLRP3 inflammasome and the subsequent release of pro-inflammatory cytokines, contributes to neuroinflammation, neuronal death, and functional impairment, playing a crucial role in neurodegenerative diseases." (PMID 40552323, 2025). "NLRP3 inflammasome contributes to innate immune‐mediated inflammation and plays a crucial role in the pathogenesis of various autoinflammatory, metabolic, and neurodegenerative diseases." (PMID 39119947, 2024). "Previous studies have suggested that the specific abnormal deposition of specific proteins may be a trigger for NLRP3 inflammasome activation in neurodegenerative diseases." (PMID 39683782, 2024). "Therefore, the NLRP3 signaling pathway is a promising therapeutic target for the treatment of neurodegenerative diseases, including VaD." (PMID 39764140, 2024). "The role of NLRP3 inflammasome was elucidated in host defense against pathogens, and their abnormal activation correlated with a variety of diseases, including cardiovascular, diabetic, and neurodegenerative diseases." (PMID 39538371, 2024). "By assessing its effects on the NLRP3 inflammasome pathway, this research seeks to demonstrate irisin’s ability to modulate various inflammatory and anti-inflammatory pathways involved in the pathogenesis and progression of neurodegenerative diseases." (PMID 39683782, 2024). "The NLRP3 inflammasome contributes critically to detrimental inflammation and immune-mediated tissue damage in autoinflammatory, autoimmune, and immunometabolic and neurodegenerative diseases." (PMID 38519142, 2024). "Indeed, there are numerous disease states in which NRF2 activation and NLRP3 inhibition are known to be beneficial including neurodegenerative diseases, metabolic diseases, gastrointestinal diseases, and autoimmune disorders." (PMID 38659753, 2024). "The search for potent and brain penetrant inhibitors of NLRP3 has become an area of drug discovery focus in recent years with biological validation relying heavily on data generated in various rodent models of neurodegenerative disease with a reference compound MCC950." (PMID 37575265, 2023). "Furthermore, in the microglia of the nervous system, the NLRP3 inflammasome can sense protein misfolding deposition or amyloid β (Aβ) aggregation and be activated to promote the occurrence and progression of neurodegenerative diseases." (PMID 37370025, 2023). "NLRP3 inflammasome activation and mitophagy impairment was involved in neurodegenerative disease." (PMID 36696410, 2023). "NLRP3 inflammasome activation is closely related to neurodegenerative diseases, such as PD." (PMID 36925673, 2023). "The NLRP3 inflammasome is involved in and drives the development of neurodegenerative diseases." (PMID 37370025, 2023). "Within the scope of this review, experimental and human studies evaluating the role of NLRP3 inflammasome activation and the efects of its inhibition in neurodegenerative diseases frequently encountered in society have been compiled with studies from past to present." (PMID 39109852, 2023). "Notably, increasing evidence indicates that the activation of the NLRP3 inflammasome plays a pivotal role in driving neuroinflammation in neurodegenerative diseases." (PMID 38139851, 2023). "The anti-hyperglycemic drug glibenclamide (Glb) might represent an interesting therapeutic option in human neurodegenerative diseases because of its anti-inflammatory activity and its ability to downregulate activation of the NLRP3 inflammasome." (PMID 38004455, 2023).
neurodegenerative disease (continued). "Given clinical advancement of NLRP3 inhibitors in neurodegenerative disease, we questioned whether NLRP3 inhibition is sufficient to mitigate cytokine release and pyroptosis downstream of other inflammasomes such as NLRC4." (PMID 37575265, 2023). "This shows that the NLRP3 inflammasome may be an important marker in the treatment of neurodegenerative diseases." (PMID 35219323, 2022). "Whereas, accumulation of Alu RNA was observed in a variety of degenerative brain diseases, researchers speculated that Alu RNA may be involved in the neuroinflammatory process of multiple neurodegenerative diseases by regulating inflammasome NLRP3 expression." (PMID 36034298, 2022). "In addition, it was shown that increased ROS, which is duo to impaired mitophagy, contributed to NLRP3 inflammasome signaling activation in neurodegenerative diseases." (PMID 35993019, 2022). "Interestingly, a growing body of evidence suggests a role of NLRP3 inflammasome as a target to treat neurodegenerative diseases." (PMID 35563447, 2022). "Our findings supported those suggesting that SPMs could modulate microglia activation, M2 polarization and even NLRP3 inflammasome activation in neurodegenerative diseases." (PMID 36670960, 2022). "Although we identified the role of p38 in the activation of NLRP3 inflammasome in α-synucleinA53T mice, the mechanism may be applicable in other neurodegenerative diseases." (PMID 34930303, 2021). "Several studies presented in this review have already shown that modulating NLRP3 inflammasome expression and activation inherent potential to delay the progression and impact of neuroinflammation in a number of neurodegenerative disease models, highlighting the importance of immune regulation." (PMID 33776778, 2021). "Notably, the activation of NLRP3 inflammasome has been proved to be involved in the pathogenesis of many neurodegenerative diseases, including AD and PD." (PMID 34925379, 2021). "Nonetheless, more specific drugs like NLRP3 regulators 49 could enable a more direct targeting of the inflammasome in neurodegenerative diseases." (PMID 34522221, 2021). "It is interesting to highlight that just NLRP3 expression remains at 24 h, and these data were confirmed by IL-1α secretion, validating the timepoints that interplay between these phenomena and supporting the role of inflammasome in neurodegenerative diseases." (PMID 33946176, 2021). "Thus, the expansion on the potential effect of fucoxanthin in the treatment of inflammatory and neurodegenerative diseases related to NF-κB signaling and NLRP3 inflammasome, is encouraged for further studies." (PMID 33436909, 2021). "Besides this, the NLRP3 inflammasome activation plays a fundamental role also in the immune response and in neurodegenerative disease, as AD." (PMID 34209586, 2021). "All the results suggest the p38–TFEB pathway could be a potential treatment target for NLRP3 inflammasome-driven neurodegenerative diseases." (PMID 34930303, 2021). "Therefore, the NLRP3 inflammasome plays a very important role in various human diseases, such as pathogen infection, autoimmune diseases, neurodegenerative diseases, and cancer." (PMID 34925047, 2021). "Moreover, NLRP3 inflammasome has garnered much attention in a variety of neuroinflammatory and neurodegenerative diseases." (PMID 33717152, 2021). "All these findings highlighted a fundamental role of the NLRP3 inflammasome in the progression of AD and suggested that the pharmacological inhibition of the NLRP3 may represent a turning point in treating neurodegenerative diseases." (PMID 34209586, 2021). "Since NLRP3-dependent pyroptosis has been reported to be involved in the progression of neurodegenerative diseases, this result suggests that curcumin may be useful as pharmacological strategy for neurodegenerative diseases." (PMID 34443381, 2021).